NF2 (NF2, moesin-ezrin-radixin like (MERLIN) tumor suppressor)
Diseases named in the same sentence as NF2 in open-access papers (continued):
Sharing a sentence is not in itself a finding about the gene and the disease.
tumor (continued). "NF2 is typically examined in tumor tissues at the gene level to screen for gene deletion, i.e. LOH or mutational inactivation." (PMID 23308224, 2013). "Conversely, the group of proteins detected in low quantities in exosomes compared to cells included important tumor suppressors such as NF2 and tuberin." (PMID 24066071, 2013). "Neurofibromatosis type 2 protein (NF2) has been shown to act as tumor suppressor primarily through its functions as a cytoskeletal scaffold." (PMID 23308224, 2013). "Instead, our data suggests that NF2, specifically its tumor suppressive FERM domain, facilitates the proteasomal degradation of ubiquitin bound T-antigen." (PMID 23308224, 2013). "Though NF2 is traditionally viewed as a cytoplasmic scaffold, it also has tumor suppressive roles in the nucleus." (PMID 23308224, 2013). "In this study, we provide a new mechanism of tumor suppression by NF2 and demonstrate inhibition of JCV T-antigen expression." (PMID 23308224, 2013). "The Schwann cell origin of DFTD makes the tumour suppressor NF2 a particularly interesting gene to examine more closely in future studies." (PMID 22359511, 2012). "Genomic DNA (blood and tumor DNA) from all 30 patients was investigated for LOH using three highly polymorphic microsatellite markers near the NF2 gene region: two flanking markers (D22S268 and D22S275) and one intragenic marker within intron 1 (D22S929)." (PMID 22295085, 2012). "The sporadic VS tumours are generally unilateral, and the familial forms are bilateral and are also known as neurofibromatosis type 2 (NF2)." (PMID 23304241, 2012). "The high tumor burden, tumor progression and the patient's young age at onset of tumors fit a classification of severe NF2." (PMID 22436304, 2012). "This study investigated the genetic alterations in sporadic VS, including mutations, loss of heterozygosity (LOH), and epigenetic alterations of the NF2 gene, and compared these alterations with the tumor behavior." (PMID 22295085, 2012). "Merlin/Nf2 is a well-known tumor suppressor and there is suggestive experimental evidence in the literature consistent with our prediction." (PMID 23272121, 2012). "The present study analyzed the genetic alterations in sporadic VS, including mutations, loss of heterozygosity (LOH), and epigenetic alterations of the NF2 gene, and correlated these alterations with tumor behavior in Korean patients." (PMID 22295085, 2012). "The authors suggest that in the future, the goal should be to find a protein that replaces the defective “merlin” in NF2 patients, which would then act to suppress tumor growth and cell adhesion in patients with NF2." (PMID 20657692, 2010). "As 25–30% of NF2 patients are mosaic frozen tumour should be taken at operation (with patient consent) for genetic tests." (PMID 19545378, 2009). "Because detection of tumours at an early stage is effective in improving the clinical management of NF2, pre-symptomatic genetic testing is an integral part of the management of NF2 families." (PMID 19545378, 2009). "The tumours in NF2 are more difficult to treat than those of sporadic unilateral VS, as NF2 VS are often multifocal, appearing "like a bunch of grapes" around the vestibular nerve in particular." (PMID 19545378, 2009). "In particular, studies using NF2-derived tumour tissue reveal elevated levels of phosphorylated Akt." (PMID 19545378, 2009). "The PI3K-Rac-Rho pathway is involved in cell motility and is negatively regulated by merlin, the protein product of the neurofibromatosis type II (NF2) tumor suppressor gene that links the cytoskeleton to the membrane." (PMID 19777070, 2009). "Our findings indicate that patients with a ring 22 should be monitored for NF2-related tumours starting in adolescence." (PMID 19772601, 2009). "As such NF2 was one of the first inherited tumour prone disorders to be localised to a specific genetic location." (PMID 19545378, 2009).
tumor (continued). "Heterozygous Nf2+/−-mutant mice develop a spectrum of unusually highly metastatic tumours, mainly osteosarcomas, fibrosarcomas, and liver carcinomas, that exhibit loss of the wild-type allele." (PMID 17971776, 2008). "Although we were unable to demonstrate that the recombination event directly affected the coding regions of NF2, we nevertheless conclude that both tumours must have a common origin." (PMID 18087273, 2008). "Methylation within the NF2 promoter region was only identified at a single CpG site in one tumor sample." (PMID 17222329, 2007). "Merlin, the product of the Neurofibromatosis type 2 (NF2) tumor suppressor gene, belongs to the ezrin-radixin-moesin (ERM) subgroup of the protein 4.1 superfamily, which links cell surface glycoproteins to the actin cytoskeleton." (PMID 16324214, 2005). "LOH data support this conclusion and that the putative tumour-suppressor gene lies distal to NF2, beyond D22S283." (PMID 7947096, 1994). "Hazard ratios for tumor progression according to NF2 and marginal dose < 11 Gy." (PMID 41454441, 2026). "Notably, while xenograft tumors were successfully established by transplanting KPT cells from cultures 3 (n = 6) and 4 (n = 7), NF2 inactivation significantly increased the tumor size compared with their KPT counterparts (n = 7 and 5, respectively)." (PMID 41480763, 2026). "Mechanistically, NF2 inactivation induced intrinsic PDAC-associated transcriptomic changes, including alterations in ECM components and elevated niche factor expression, which predisposed cells for tumor initiation and progression." (PMID 41480763, 2026). "Although the mechanisms remain unclear, prior reports suggest that multifocal tumor growth, peritumoral edema, and cortical irritation may contribute to higher seizure burden in NF2 patients." (PMID 41526775, 2026). "However, in addition to the EWSR1::VGLL1fusion, our patient’s tumor had a nonsense mutation in LZTR1, oneof the two genes with germ-line mutations implicated in non-NF2 associatedschwannomatosis." (PMID 41522855, 2026). "Despite the potential impact of selecting patients with a minimum of 2 years of follow‐up from the PMS‐overall cohort, the results consistently pointed toward a trend of early tumor control failure among patients with NF2‐VS who were younger than 20 years of age." (PMID 41454441, 2026). "However, among the NF2‐VS group, significantly poorer tumor control was evident among patients younger than 20 years of age after SRS compared to older patients." (PMID 41454441, 2026). "Nevertheless, our results give insights into the tumour features and cellular pathways that may be amenable for targeting to improve treatment of NF2 SWN-related VS." (PMID 40140675, 2025). "This indicates that hypermethylation did not considerably contribute to NF2 gene silencing in these patients, suggesting that alternative mechanisms such as mutations or deletions have a more crucial role in tumour development in NF2-related VSs." (PMID 40843672, 2025). "Notably, most of these genes (Kmt2d, Bcor, Smad, Nf2, Lats1) are tumor suppressors in human cancers." (PMID 38853928, 2025). "Therefore, it was indicated that while epigenetic changes can influence tumour biology in NF2, additional mechanisms are likely involved in most cases, and this warrants further investigation." (PMID 40843672, 2025). "One NF2-mutated BIOB tumor showed isolated brain invasion without mitotic activity or atypical morphological criteria." (PMID 40951339, 2025). "Consequently, a significant amount of research has commonly utilized the IOMM-Lee and CH157-MN cell lines to investigate the effects of drugs and compounds on tumor proliferation due to their specific NF2 expression." (PMID 39894505, 2025). "This variability in the outcomes may be explained by several variables as tumor size, preoperative hearing, irradiation, NF2 status or the degree of tumor resection in surgical cases." (PMID 39914046, 2025).
tumor (continued). "Similarly, NFM-1, the ortholog of Merlin/NF2, the well-established co-regulator of Wts in Drosophila and a tumor suppressor in mammals, acts in parallel to WTS-1 to support intestinal polarity and developmental progression." (PMID 40909657, 2025). "The use of two separate tumours has been shown to increase detection of mosaic NF2 variants when the variant is not detectable in blood, even on a high read-depth assay." (PMID 41284083, 2025). "In contrast to uVS, NF2-related bVS may develop at a younger age, show a higher tumor progression rate, and respond less favorably to standard treatment options." (PMID 39941762, 2025). "In NF2-deficient cells, malonyl-CoA accumulation and malonylation of CPT1C (an ACC-regulated enzyme in the brain) are linked to aberrant mTOR signaling and lipid accumulation, potentially fostering a tumor-permissive environment." (PMID 41107644, 2025). "In addition, pharmacological inhibition of DHODH exerted a robust antiproliferative effect on NF2-deletion PM cells, as evidenced by reduced cell viability, colony formation, and tumor spheroid formation." (PMID 40707702, 2025). "Driver mutations were associated with a specific tumour subtype presenting secretory subtype (KLF4K409Q) and meningothelial (AKT1E17K), however, multiple histological subtypes could be observed in the NF2-driver mutation group." (PMID 40562609, 2025). "Groups of patients with tumours largely confined to the peripheral nerves and spine, with sparing of the eighth nerve usually do not to have an identifiable NF2 pathogenic variant identifiable in blood." (PMID 41160189, 2025). "This study aims to provide a comprehensive review of the currently available evidence regarding the use of bevacizumab in pediatric patients with NF2-related schwannomatosis, with a focus on its effects on hearing, tumor progression, and treatment-related toxicity." (PMID 39941885, 2025). "If a shared NF2 variant is seen across the unique tumour samples and not found (or at low level) in blood, this confirms mosaic NF2-SWN." (PMID 41160189, 2025). "VS tumours in individuals with NF2 SWN are heterogeneous both clinically and therapeutically, and as we have demonstrated this heterogeneity extends to the histopathological, cellular and spatial levels, highlighting potential for improved patient stratification and better management of the disease." (PMID 40140675, 2025). "In all patients with NF2 (100%), two or more hits were detected in the tumor DNA." (PMID 39941762, 2025). "Immunoblot analysis further revealed that the expression level of NF2 protein in the microRNA‐223‐3p mimic group was significantly decreased compared to the control group, suggesting that microRNA‐223‐3p may promote tumor growth by downregulating NF2 protein." (PMID 39712860, 2025). "Children with NF2 have lifelong, unpredictable tumor growth potential." (PMID 40852360, 2025). "Tumor size was significantly larger in the NF2 subgroup (mean 4.9 cm; p = 0.013)." (PMID 40951339, 2025). "Notably, tumor suppressors like NF2 (Merlin) and RASSF family members exert anti-cancer effects through cytoskeletal interactions and membrane protein regulation, essential for cellular homeostasis maintenance." (PMID 40486910, 2025). "However, DDR1 knockdown significantly reduced GSH levels and GPX4, SLC7A11 and ZEB1 expression and increased MDA and Fe2+ levels, as well as ACSL4, E‐cadherin, p‐YAP and p‐NF2 expression levels in tumour tissues." (PMID 40105492, 2025). "Using proteomics, we showed that the NF2−/− tumours divided into two distinct groups with distinct underlying mutational spectrum, NF2 clusters 1 and 2, independent of NF2 severity score, chromosome loss, CDKN2A/B and TERT mutations." (PMID 40562609, 2025). "Overall, cooccurring deficiencies in BAP1, NF2, and CDKN2A/B might play an instructive role in tumor immunity and are closely related to patient prognosis." (PMID 38879686, 2024).
tumor (continued). "Recently, several studies have linked NF2 mutations to the tumor immune microenvironment (TIME), which may provide a more targetable avenue for use of immunotherapeutics in NF2-mutated tumors." (PMID 39796693, 2024). "Understanding the composition of the TME will also benefit in the research of a potential systemic therapeutic approach not only for patients suffering from VS, who are not suitable for surgery due to age, comorbidity, or size of the tumor, but even more importantly for patients suffering from NF2." (PMID 38817895, 2024). "Pediatric patients with NF2 often present more aggressive VS growth patterns and may experience different treatment outcomes, as seen in studies where tumor responses and hearing improvements were notably lower in children compared to adults." (PMID 39685944, 2024). "In addition, PAK1 specific inhibition has been shown to be moderately effective in reducing tumor size and increasing survival of a genetically engineered mouse model of NF2." (PMID 39083549, 2024). "This study provides the first evidence for an important tumor inhibitory effect of KAT2B in CCA through regulation of NF2-YAP signaling and suggests that this signaling cascade may be therapeutically targeted for CCA treatment." (PMID 38641672, 2024). "Thus, it is possible that tissue mechanics interplay with signaling pathways to regulate tumor induction in NF-2." (PMID 39415595, 2024). "Besides NF2, the same study found that several other tumor suppressors, including OPCML, Cav-1, and UGT2B17, showed a loss of tumor suppressive effects." (PMID 39796693, 2024). "On the other hand, NF-2 copy number loss was associated with lower SWI signal intensity, a growth pattern described as “en plaque”, and the presence of calcification within the tumor." (PMID 38611661, 2024). "The NF2 gene is a member of the ERM (ezrin, radixin, moesin) family of cell adhesion protein-encoding genes and codes for the protein merlin, which acts as a tumor suppressor." (PMID 39415595, 2024). "In addition, the NF2 LOF mutants promoted the NF2 KO IOMM-Lee xenograft tumor growth, while treatment with JNK inhibitor JNK-IN-8 significantly attenuated it." (PMID 39572544, 2024). "Interestingly, NF2, a key tumor suppressor, responsible for activation of LATS1 (Large tumor suppressor homolog 1) and increased YAP1 phosphorylation, was significantly up‐regulated after silencing of TRIM65 expression." (PMID 39005234, 2024). "Moderate ductular reaction in the portal tract areas was already found in 2- and 6-week-old Nf2-mutant mice and progressed in the 20- to 32-week-old cohort, ultimately leading to a massive tumor-like ductular process radiating from and bridging portal areas in livers of 48-week-old Nf2-mutant mice." (PMID 37174657, 2023). "Loss of chromosome 1p was highly associated with NF2 mutated tumours, whereas loss and gain on chromosome 17q were isolated to tumours in which no NF2 mutation was detected." (PMID 36882706, 2023). "Nf2 deficiency leads to the aberrant activation of cancer pathways, including the Hippo-YAP pathway, and promotes malignant progression in various types of tumor." (PMID 37730636, 2023). "However, alternative conformations have been proposed as well and the exact mechanism how NF2 conformation is regulated and how NF2 conformation influences tumor suppressor activity remains elusive (Petrilli & Fernández-Valle, 2016)." (PMID 37280085, 2023).
tumor (continued). "Inactivating mutations and deletions of 3 tumour suppressor loci, namely CDKN2A/B, NF2, and BAP1 predominate, with functional loss of each tumour suppressor occurring in over 50% of cases and single or combinatorial loss of the 3 loci found in all possible permutations." (PMID 37441092, 2023). "Of note, CNAs on 22q were present in tumours from six patients including two patients who had tumours with no NF2 mutations detected, including a large copy number gain in region 22q containing NF2 in patient F." (PMID 36882706, 2023). "Also, it helps to find new treatments by reversing pathologic genetic/epigenetic modifications to replace normal merlin function, decrease tumor burden, preserve hearing, and improve survival of patients with NF2." (PMID 37217995, 2023). "Patients in our cohort with tumours with NF2 mutations showed frequent CNAs with similar patterns across patients, in contrast, tumours with no NF2 mutation detected showed less frequent CNAs." (PMID 36882706, 2023). "The fourth metastasizing tumor had copy-number losses in NF2 and PTEN." (PMID 36641486, 2023). "Tumours from patients F and H (tumours in which no NF2 mutation was detected) shared similar patterns of CNAs, including an interesting combination of loss and high gain (x4) on chromosome 17q." (PMID 36882706, 2023). "Neurofibroma protein 2 (NF2), a classical tumor suppressor that controls tumor growth and regulates angiogenesis in the tumor microenvironment, has been reported to regulate cGAS-STING signaling through NF2 mutation mediated-LLPS." (PMID 36860877, 2023). "Predictors composed of mixed clinical and omic features were also considered, finding good and performance, confirmed in independent cohorts, for a fingerprint composed of three well known clinical parameters (PSA, Gleason primary score, and tumor stage) and expression levels for NF2 and CDKN1B." (PMID 37188913, 2023). "Two patients with tumours without detected NF2 mutations showed a combination of loss and high gain on chromosome 17q." (PMID 36882706, 2023). "Moreover, the patient who exhibited the NF2 R57* mutations in both plasma and tumor tissue displayed a notably higher VAF in the plasma in comparison to the tumor, an unexpected finding." (PMID 38259646, 2023). "Therefore, despite the presence of NF2 alterations, it is possible that NF2 gene abnormalities were overlooked depending on the location of the tumor tissue analyzed." (PMID 37180489, 2023). "It has been shown that NF2 mutant tumor cells interact with FAK inhibition." (PMID 37760490, 2023). "Four patients in our cohort had tumours with NF2 mutations, none of our patients were known to have NF2 germline mutations." (PMID 36882706, 2023). "The tumor was WHO grade 2–3 and next-generation sequencing was notable for TERT promoter mutation, homozygous deletion of CDKN2A, and high variant allele frequency of NF2." (PMID 37025757, 2023). "In contrast, tumours without a detected NF2 mutation (patients A, D, I and J) show limited CNAs including both patients with NAB2-STAT6 inversion (patients D and J)." (PMID 36882706, 2023). "To date, the restricted availability of tumor tissues and, more importantly, the absence of in vitro and in vivo model systems are barriers to clinical studies of NF2-associated tumors and deciphering the biological mechanisms related to their progression." (PMID 37217995, 2023). "Patient B (NF2-mutated tumours) on the other hand, had TERT promoter and NF1 mutations in all tumour grades, suggesting that a TERT promoter mutation is not an oncogenic driver, from Grade 2 to 3, as it was also present in the Grade 2 tumour." (PMID 36882706, 2023).